IFNGR2 (interferon gamma receptor 2)
Diseases named in the same sentence as IFNGR2 in open-access papers (continued):
Sharing a sentence is not in itself a finding about the gene and the disease.
tumor (continued). "To test this hypothesis, we inoculated mice with a mixture of WT and IFNγR2-mutant tumor cells at a 1:1 ratio, and then treated the mice with anti-PD-L1 antibody." (PMID 32001684, 2020). "For example, Ifngr2 (encodes the receptor for type 1 cytokine interferon-γ (IFNγ)), was enriched in cLTMR neurons, suggesting these neurons preferentially responded to IFNγ-producing cells, such as CD8+ T cells and NK cells, which are mediators of anti-viral and anti-tumor immunity." (PMID 38806708, 2024). "The DEGs included genes involved in cell proliferation and migration (e.g., COL11A1), tumor‐promoting factors that degrade the extracellular matrix (e.g., MMP11), as well as immunosuppressive (TGFB1) and proinflammatory responses (TNFRSF6B, IFNGR2, GSDMB)." (PMID 40952312, 2025). "The immune escape from T cells caused by the knockout of genes IFN-γ signaling pathway (JAK1, JAK2, Ifngr2) and antigen presentation pathway (TAP1, TAP2, B2M) promotes tumor vulnerability to NK cells." (PMID 40191187, 2025). "IFNGR2 and VEGFBR1 also impact tumor progression by modulating immune recognition, nutrient supply, and the metastatic potential of tumor cells." (PMID 40181976, 2025). "The results showed that the expression levels of PYGB, IFNGR2, TICAM1, STAT6 and VPS4B in CHOL tissues showed an overall upward trend compared with non-tumor hepatobiliary duct tissues." (PMID 36936916, 2023). "Our prognostic signature consists of five genes, PYGB, IFNGR2, TICAM1, STAT6, and VPS4B, each of which plays a critical role in necroptosis and tumor progression." (PMID 36936916, 2023). "For instance, IFN-γ signaling is known as an essential effector molecule for anti-tumor immune response, which must bind the IFN-γ receptor (IFNGR1 or IFNGR2) to modulate the JAK–STAT pathways and affects the immune cell activation." (PMID 34124058, 2021). "By contrast, the Oxali + anti–PD-L1 combo decreased the fractions of each tumor occupied by CD45− “cancer” cells, an effect that was most pronounced in WT tumors relative to p300 or IFNγR2 ablated tumors." (PMID 33602823, 2021). "On day 7 after tumor challenge, a 3-fold increase in the frequency of H-2Kb/SIY+ CD8+ tumor infiltrating lymphocytes (TILs) was observed in IFNγR2- and Jak1-mutant tumors compared to WT tumors." (PMID 32001684, 2020). "Consistent with our previous observations, IFNγR2- and Jak1-mutant B16F10 tumors also exhibited slower tumor growth, although the difference in growth rate was less pronounced presumably due to decreased antigenicity." (PMID 32001684, 2020). "As with the generation of IFNγR2- and Jak1-mutant B16.SIY tumor cells, we generated MC38 IFNγR2- and Jak1-mutant tumors by establishing a founder cell line and a similar single-cell CRISPR/Cas9 mutagenesis method." (PMID 32001684, 2020). "To be able to examine the role of tumor-intrinsic IFN-γ signaling in the antitumor immune response in vivo, we generated IFNγR2- and Jak1-mutant B16.SIY tumor cell lines by single-cell cloning using the sgRNAs identified from the CRISPR/Cas9 screen." (PMID 32001684, 2020). "In practice, when we predict a KP tumor patch on GSM5808054 from the unperturbed state to Ifngr2 KO that appears only on GSM5808056, kNN has no relevant neighbors to copy and fails to express the correct shift in rGEX." (PMID 41292874, 2025). "Increased expression of Ifngr1, Ifngr2 and Ifnar2 in cluster 0 of the CAR-T-treated group (compared to mock-T-treated), indicates this could be a tumor adaptive mechanism to Ifn-γ and Ifn-α signaling mediated by CAR-T cell therapy." (PMID 40568084, 2025). "For IFNGR2, STAT1 and MYC, both sgRNA pools significantly increased the number of eGFP positive 2D3TCR/dCas9 cells (right), in line with their role as positive regulators of PD-L1 expression in tumor cells." (PMID 39497819, 2024). "The mode of action of TGFB2 is complex in the LGG TME, involving the activation of IFNGR2 pathways, tumor cells, and TAMs independent of the IDHwt genotype of tumors." (PMID 38539537, 2024).
tumor (continued). "In a preclinical model, IFNGR2 and JAK1 KO cells outgrew wild-type cells in a mixed tumor model." (PMID 37803324, 2023). "To explore the role of RUNX1 in tumor progression and the immune response of LGG, we explored the highest correlation gene with RUNX1 transcript level through UALCAN analysis and identified IFNGR2 as the target gene." (PMID 36321611, 2023). "IFNγ receptor genes IFNGR1, IFNGR2 and the downstream effector IRF1 have been reported to be expressed on a PNET cell line QGP-1, and IFNγ treatment could inhibit tumor growth and induce apoptosis in vitro, indicating a direct anti-PNET effect of IFNγ." (PMID 38020179, 2023). "The tumor was split into two fractions, one fraction was mashed and assessed for IFN-γ content by ELISA within the interstitial fluid, and the other was used to measure the frequency IFNγR2-mutant and WT tumor cells." (PMID 32001684, 2020). "To this end, we inoculated mice with WT:WT or WT:IFNγR2-mutant tumor cells and administered 50 μg of recombinant mouse IFN-γ i.p. on days 7, 10, 13, and 16 and analyzed tumor cell composition on day 18 after tumor cell inoculation." (PMID 32001684, 2020). "We also observed that tumor cells that engaged senescence-related transcriptional programs, or “Sen-High” cells, upregulated IFN-γ signaling machinery, including Ifngr1, Ifngr2, Jak1, Jak2, Irf1, and Stat1, as well as IFN-γ target genes Cxcl9, Cxcl10, and Tap1." (PMID 40299790, 2025). "Particularly noteworthy, the increase in interaction pairs involving IFNG_(IFNGR1+IFNGR2) in OT samples, indicating that the combination therapy enhances the secretion of interferon by CD8+ T cells, which in turn interact with malignant cells to execute anti‐tumour effect." (PMID 39415331, 2024). "To mimic IFN conditions in the tumor microenvironment (TME), we added IFNγ exogenously in SCC cells since (i) IFNγ pathway is the most significant pathway negatively regulated by TP63, (ii) IFNγ receptors (IFNGR1, IFNGR2) have higher expression than IFNα receptors (IFNAR1, IFNAR2) in SCC cells." (PMID 38509096, 2024). "IFNGR2, KLF10, PLAUR, MSN, and IKBIP, whose coefficients of risk score were >0, had positive correlations with risk score, stromal score, immune score, and ESTIMATE score and negative relationships with tumor purity." (PMID 38137116, 2023). "Indeed, under these conditions, progressive tumor growth was no longer observed, with no detectable outgrowth of IFNγR2-mutant tumor cells." (PMID 32001684, 2020). "To address the mechanism behind the selection process of IFNγR2-mutant tumor cells, we hypothesized that IFN-γ-insensitive tumor cells could escape the direct antitumor effects of IFN-γ, which would be preserved in tumor cells that have intact IFN-γ-signaling." (PMID 32001684, 2020). "We then discussed the effects of other cell types on epithelial cells in tumor tissue, and the results indicated that immune cells could regulate epithelial cells through specific ligand–receptor pairs, such as TNFSF14-TNFRSF14, MIF-(CD74+CD44), IFNG-(FINGR1+IFNGR2), CXCL12-ACKR3, and CXCL11-ACKR3." (PMID 36569924, 2022). "Therefore, other factors, such as upregulation of PD-L1 on tumor cells, could contribute to the negative correlation between IFNGR2 expression and the overall survival of AML and KIRC patients." (PMID 31921143, 2019). "Of note, p300 or IFNγR2 ablation had little effect on tumor-infiltrating effector CD8+ T cells, whose numbers were similarly increased after Oxali + anti–PD-L1 treatment in p300- or IFNγR2-expressing and nonexpressing tumors." (PMID 33602823, 2021). "While tumor control was maintained in NK-depleted mice, CD8-depleted mice failed to control IFNγR2-mutant tumors and no synergy was observed when both NK and CD8+ T cells were depleted." (PMID 32001684, 2020).
infection (19 papers, 2009 to 2025). The state of being infected such as from the introduction of a foreign agent such as serum, vaccine, antigenic substance or organism. "IFNGR2 is also downregulated in monocyte-derived human macrophages following infection by Leishmania major." (PMID 39028711, 2024). "The clinical manifestations of complete deficiency of IFNGR2 are similar to those of complete IFNGR1 deficiency, and patients present with severe or even fatal infection early in life." (PMID 36569938, 2022). "(e) Immunofluorescence images of intestinal crypts of naïve or T. gondii-infected WT, E- Ifngr2 KO, and PC- Ifngr2 KO mice treated intravenously with propidium iodide (PI) on day 6 post infection." (PMID 34633285, 2021). "Or if these cells are re-circulating from a site of infection, that they are reprogrammed on egress, with concurrent down-regulation of some markers, chemokines and cytokines upon re-entry to the periphery e.g. IFNγR2." (PMID 27228113, 2016). "This would imply that either these peripheral cells are responding to a referred interferon signal produced at the site of infection with suppression of IFNγR2 expression." (PMID 27228113, 2016). "The expression of IFNγR2 on splenic CD4+ T cells was reduced on day 7 post-infection in the FeD mice." (PMID 25768944, 2015). "Intriguingly, the IFNγR2 subunit distribution pattern was markedly altered from the very early hours of infection through the late hours, when bulk of the proteins were recovered from the non-raft fractions, denoting complete detergent solubilization." (PMID 21931549, 2011). "During infection, restraint in IFNγR2 recruitment in raft fraction even in the presence of IFNγ, suggests that the association of IFNγ-R1 and -R2 in LD-MØ is defective." (PMID 21931549, 2011). "In response to P. aeruginosa, genes associated with IFN-γ response to infection (CXCL10, IL-24, IFNγR2) and other mediators of anti-infectious responses (CSF2, MMP1, MMP3, TLR2, S100 calcium-binding proteins A) were markedly up-regulated in wild-type TG cells." (PMID 19399182, 2009). "Notably, myeloid cells in AG ferrets showed significantly elevated expression of inflammatory cytokines, including IL-1β, IL-10, IL-18, NFκB1, and S100A8, as well as upregulated IFNGR2 expression throughout infection, especially 4dpi." (PMID 40794649, 2025). "Additionally, the gene expression analysis of the cultivated epithelial cells showed no expression of IFN-γ, but increased expression of IFN-γ-receptor (Ifngr2) upon infection." (PMID 35027063, 2022). "Consequently, mice with DC-specific IFNγR2 ablation harbored diminished numbers of T-bet+ Th1-Treg cells and suffered severe infection-induced Th1 immune pathology." (PMID 25658840, 2015). "Conversely, infection for 4 hr markedly reduced the extent of IFNγR2 coprecipitation with IFNγR1 even in IFNγ stimulated condition, while the level of coprecipitated IFNγR2 went below detection level with increasing time of infection." (PMID 21931549, 2011). "Macrophages were identified as the cluster expressing high levels of IFNGR1 and IFNGR2, then we investigated if macrophages responded to IFN-γ and were regulated by IFN-γ after the infection." (PMID 37180169, 2023). "(a) qRT-PCR analysis of relative Lyz1, Defa23, and Defa24 expression measured in the small intestines of WT, E-Ifngr2 KO, and PC- Ifngr2 KO infected orally with 20 cysts per mouse of the ME49 T. gondii on day 7 after infection (n=6) or uninfected controls (n=6)." (PMID 34633285, 2021). "In contrast, the lack of IFNγR2 intrinsic signalling prevented the expansion of the T cell compartment following infection that was seen with WT T cells, both in BM and in the spleen." (PMID 28671989, 2017). "The percentages of IFNγR2- and T-bet-expressing CD4+ T cells were increased in both groups on day 7 post-infection compared to day 3 post-infection; however, the percentages of IFNγR2+ and T-bet+ CD4+ T cells were markedly reduced in the FeD mice on day 7 post-infection." (PMID 25768944, 2015).
infection (continued). "However, in RAW 264.7 cells transduced with positive control shRNAs to knock down gene expression of IFN-γ receptor 1 (Ifngr1), 2 (Ifngr2) or Ticam2, the antiviral control by IFN-γ was greatly compromised and a 3- to 4-fold increase of infection efficiency was observed." (PMID 25268627, 2014). "Most striking of these results is that, though we could recover some ligand engaged IFNγR1 from non-raft portions at 4 hr post infection, IFNγR2 was only detectibly coimmunoprecipitated from the raft fractions." (PMID 21931549, 2011). "To explore whether SECoVs infection affects IFN receptors expression, we next compared the receptor expression of the three types of IFNs, including type I IFN receptors (IFNAR1 and IFNAR2), type II IFN receptors (IFNGR1 and IFNGR2), and type III IFN receptors (IL10RB and IFNLR1)." (PMID 35126380, 2021). "It is worthy of note that at late hours of infection, though engaged IFNγR1 and IFNγR2 were simultaneously present in the non-raft fractions, they could not generate any productive interaction as evidenced by the complete absence of IFNγ triggered CoIP and/or phosphorylation signal." (PMID 21931549, 2011). "On day 3 post-infection, IFNγR2 was expressed on a low percentage of CD4+ T cells and the percentage of IFNγR2+ CD4+ T cells was not significantly different in the FeD mice compared to the control mice." (PMID 25768944, 2015).
cancer (18 papers, 2014 to 2025). A tumor composed of atypical neoplastic, often pleomorphic cells that invade other tissues. "Another relevant LR biomarker was IFNG binding to IFNGR1 and IFNGR2 (positive association for 17 of the 18 cancer types)." (PMID 34430923, 2021). "Moreover, the expression levels of IFNGR2 and C8ORF37 were both significantly negatively correlated with the prognosis of patients with cancer associated with malignant biliary strictures, suggesting that eccEnhancers that activate IFNGR2 or C8ORF37 may contribute to poor outcomes." (PMID 39920810, 2025). "Despite the relatively small size of the patient cohort, a trend of better overall survival was observed in AML patients with cancer tissues that had lower expression of IFNGR2 and higher expression of NKG7." (PMID 31921143, 2019). "The result of our analysis implied that higher expression of IFNGR2 in cancer cells and its downstream signaling is unfavorable in AML and KIRC patients, potentially due to constraints on NK cell activity." (PMID 31921143, 2019). "Drugs targeting TNFRSF9, IL2RA, FCGR2A, IFNGR2 were found to be potential targets for cancers." (PMID 36857861, 2023). "In addition, a previous report showed that decreased expression levels of IFNGR2 are a risk factor for tumorigenesis in humans and may involve IFN-γ dependent cancer immunosurveillance." (PMID 31795085, 2019). "For instance, genes like NOTCH2, IFNGR2, and MDM2 are upregulated in the Pathways in Cancer—specifically, NOTCH2 and IFNGR2." (PMID 40621499, 2025). "Among the enriched genes, we identified known hits that are important for immune-mediated cancer killing, e.g., STAT1 and IFNGR2." (PMID 38678024, 2024). "Among those genes are IFNGR2, PITX2, RFWD2, PPARγ, LOXL2, Rab6 and SPARC, all involved in cancer-related pathways." (PMID 24875049, 2014). "To gather information about p300 and CBP in human cancer, we examined The Cancer Genome Atlas (TCGA) dataset and found significant correlations between EP300 or CBP mRNAs and genes identified by our integrative RNA-seq and ATAC-seq analyses, including RELA, STAT1, NFKB1, IFNGR2, and NLRC5." (PMID 33602823, 2021). "However, the remaining eight cancer-specific DESPGs of GLB1, HSPA5, PDIA3, GNRH1, IFNGR2 ADAM9, TPST2, and TAC4) were not reported in any researches, which could be potential novel prognostic biomarkers in corresponding tumors." (PMID 31824949, 2019).
bacterial infection (4 papers, 2013 to 2024). "Functional annotation of putatively selected genes revealed that these genes were predominantly associated with immune-related functions, inclusive of genes such as C5AR1 and MYH10 (bacterial infection); ARHGEF1, ERCC2 and TRAF2 (viral infection) and IFNGR2 (both viral and bacterial infection)." (PMID 33116287, 2020). "Cxadr and Ifngr2 are usually invoked in response to viral rather than bacterial infection." (PMID 24068166, 2013).
immune disorder (3 papers, 2015 to 2024). "Another important primary immune disorder associated with increased susceptibility to mycobacterial infection is IFNGR-1 and IFNGR-2 deficiencies." (PMID 26137337, 2015).
metabolic disease (1 paper, 2023). A congenital disorder (due to inherited enzyme abnormality) or acquired (due to failure of a metabolically important organ) disorder resulting from an abnormal metabolic process. "Meanwhile, the core genes in the Lean line might be Nf2 (linking syndromic, nervous, urinary and cellular proliferative diseases), Lrp1 (linking cardiovascular and nervous system diseases and physical disorders), and Ifngr2 (linking immune, endocrine and metabolic diseases)." (PMID 36414820, 2023).
IFNGR2 also shares sentences with these, for which no sentence is quoted: infectious disease (3 papers); autoimmune disease (2); gastrointestinal disease (2); hepatocellular carcinoma (2); Kidney (2); malaria (2); acute myeloid leukemia (1); atherosclerosis (1); atopic asthma (1); breast tumor (1); Candida infections (1); cardiovascular disease (1); chronic hepatitis C (1); chronic periodontitis (1); colon cancer (1); DiGeorge syndrome (1); endometrial carcinoma (1); Fanconi anemia (1); heart disorder (1); Herpes simplex infection (1); immunodeficiency 28 (1); leishmaniasis (1); liver cancer (1); Mendelian susceptibility to mycobacterial diseases (1); multiple sclerosis (1); mycobacteriosis (1); nephrotic syndrome (1); nervous system diseases (1); neutropenia (1); obstructive lung disease (1).
A further 8 diseases each share a sentence with IFNGR2 in 1 paper.